LTA (lymphotoxin alpha)
Diseases named in the same sentence as LTA in open-access papers (continued):
Sharing a sentence is not in itself a finding about the gene and the disease.
myocardial infarction (5 papers, 2008 to 2019). Gross necrosis of the myocardium, as a result of interruption of the blood supply to the area, as in coronary thrombosis. "A recent clinical epidemiological study reveals variations in the gene encoding LTα (thereby affecting its expression and biological function) confers myocardial infarction risk." (PMID 23704873, 2013). "Several genetic and clinical studies demonstrate that variations in the gene encoding LTα (consequently affecting its expression and biological function) contribute to the risk of coronary artery disease, myocardial infarction, aortic aneurysm formation, and cerebral infarction." (PMID 23704873, 2013). "A large genome-scan in Japanese patients identified a susceptibility locus for myocardial infarction on chromosome 6p21, especially the 256A→G and T60N (also referred to as T26N in some studies) variants in the LTA gene, were associated with myocardial infarction." (PMID 18575614, 2008). "BAT1 (HLA-B-associated transcript 1), a gene with anti-inflammatory activity, and LTA (lymphotoxin alpha), a pro-inflammatory cytokines member of the TNF family have been associated with coronary artery disease and myocardial infarction." (PMID 22529863, 2012). "This study determines the roles of tumor necrosis factor-α (TNFα) and lymphotoxin-α (LTα) in post-myocardial infarction (post-MI) cardiac injury, and identifies the TNF receptor type responsible for TNFα- and LTα-mediated cardiac injury." (PMID 23704873, 2013).
periodontal disease (5 papers, 2012 to 2024). "Lymphotoxin alpha (LT-α) is a potent multifunctional immune modulator that contributes toward susceptibility to immune regulation disorders, including periodontal disease." (PMID 23050158, 2012).
Autoimmunity (4 papers, 2012 to 2022). The occurrence of an immune reaction against the organism's own cells or tissues. "Generating an inducible transgenic mouse model allowing LTα deletion at a specific time point, i.e., before or after the development of autoimmune signs, would be useful to define the potential of LTα as a new target to prevent or treat autoimmunity associated with defective T cell selection." (PMID 29593265, 2018). "Finally, from a therapeutic perspective, because Ltα deficiency increases DC and macrophage thymic entry, it would be interesting to determine whether LTα loss can protect and treat from autoimmunity." (PMID 29593265, 2018). "Interestingly, in addition to its pathogenic role, this pathway can be exploited as a biomarker of disease as we showed that LTα expression correlates with CCL19 levels and distinguishes patients with autoimmunity and dryness (Sjögren’s syndrome) from patients with dryness only (sicca patients)." (PMID 35508704, 2022).
Cirrhosis (4 papers, 2013 to 2024). A chronic disorder of the liver in which liver tissue becomes scarred and is partially replaced by regenerative nodules and fibrotic tissue resulting in loss of liver function. "Thus, 25.8% patients exhibiting genotypes TNFα308GA – LTα + 252AG and 31% patients having TNFα308GG – LTα + 252AA demonstrated ultrasound signs of cirrhosis development whereas the frequencies of portal hypertension in these two groups were 6.2% and 13.8%, respectively." (PMID 23343370, 2013).
Sjögren syndrome (4 papers, 2015 to 2022). "Thus, in order to investigate whether LTα could play a similar initiating role in the development of Sjögren’s Syndrome in humans we monitored [Ca2+]i signals in lobules prepared from minor salivary glands obtained from HV that were incubated with LTα for 16 hrs." (PMID 26365984, 2015).
Stroke (4 papers, 2020 to 2025). Sudden impairment of blood flow to a part of the brain due to occlusion or rupture of an artery to the brain. "TNFβ (also known as lymphotoxin alpha) and TNFRSF9 (also known as CD137), which activate downstream inflammatory pathways, increasing inflammation and CCL19, a protein involved in arteriole growth following ischemia that is correlated with worse outcome following stroke." (PMID 40703679, 2025).
tuberculosis (4 papers, 2013 to 2016). A chronic, recurrent infection caused by the bacterium Mycobacterium tuberculosis. "At the same time there was no case of tuberculosis among patients, both homozygous and heterozygous for LTα + 252 G alleles (p = 0.01)." (PMID 23343370, 2013). "In 9 of 108 (8.3%) of LTα + 252AA carriers, tuberculosis infection has been documented, whereas there was no case of tuberculosis among patients, either homozygous or heterozygous for LTα +252 G alleles (p = 0.01)." (PMID 23343370, 2013).
endometrial cancer (3 papers, 2020 to 2022). Primary or metastatic malignant neoplasm involving the endometrium (mucous membrane that lines the endometrial cavity). "Eight IRGs were incorporated to construct a nomogram for survival prediction in endometrial carcinoma patients, including CCR7, GNA15, GPR132, LTA, MYC, NOD2, P2RX4 and P2RY2." (PMID 36207698, 2022).
Hodgkins lymphoma (3 papers, 1998 to 2021). A heterogeneous group of malignant lymphoid neoplasms of B-cell origin characterized histologically by the presence of Hodgkin and Reed-Sternberg (HRS) cells in the vast majority of cases. "A prospective study was performed to assess the use of plasma measurement of tumour necrosis factor (TNF), lymphotoxin alpha (LT alpha) and their soluble receptors (p55 and p75) for prognostic risk assignment in 61 patients with Hodgkin's disease." (PMID 9649158, 1998).
parasitemia (3 papers, 2008 to 2024). "Mice lacking TNF receptors 1 and 2, the receptors for TNFα and LTα, had a higher peak parasitemia, reduced parasite killing in infected red blood cells (iRBCs), and delayed parasite clearance compared to control mice." (PMID 39452729, 2024).
prostate carcinoma (3 papers, 2007 to 2022). A carcinoma that arises from epithelial cells of the prostate gland. "We previously reported that a functional variant (LTA C+80A) in lymphotoxin alpha, a proinflammatory cytokine, modified the protective effect of NSAIDs on prostate cancer." (PMID 17609663, 2007).
sarcoidosis (3 papers, 2013 to 2025). Sarcoidosis is a multisystemic disorder of unknown cause characterized by the formation of immune granulomas in involved organs. "To detect variants predisposing to sarcoidosis and to identify genetic differences between patient subgroups, we studied four genes in the MHC Class III region (LTA, TNF, AGER, BTNL2) and HLA-DRA with tag-SNPs and their relation to HLA-DRB1 alleles." (PMID 28469621, 2017).
systemic lupus erythematosus (3 papers, 2013 to 2025). An autoimmune multi-organ disease typically associated with vasculopathy and autoantibody production. "In systemic lupus erythematosus (SLE), LDGs exhibit a strong pro-inflammatory role by inducing T cells to release IFN-γ, TNF-α, and lymphotoxin alpha (LTA)." (PMID 40689395, 2025).
anemia (2 papers, 2008 to 2018). A reduction in the number of red blood cells, the amount of hemoglobin, and/or the volume of packed red blood cells. "The ECM resistant, LTβR deficient mice further developed dramatic anemia, similar to LTα deficient mice (1.34±0.30×106 RBC/μL), and probably succumb of general hypoxia after 3 weeks." (PMID 18612394, 2008). "It was shown that the TNF-family members [TNF-α and lymphotoxin-alpha (LT-α)] play a key role in chronic/progressive anemia development by signaling via their dedicated receptors [TNF-R1 or p55 (CD120a), TNF-R2, or p75 (CD120b)]." (PMID 29497418, 2018). "Further, absence of LTα or LTβR did not interfere with the progression of blood stage infection, and LTα or LTβR deficient mice succumb within 3 weeks of severe parasitaemia and anaemia." (PMID 18612394, 2008). "In conclusion, the resistance to ECM development of LTα and LTβR deficient mice was not attributable to decreased parasitaemia or thrombocytopenia, and the ECM resistant mice developed very high parasitaemia and died of severe anemia within 3 weeks." (PMID 18612394, 2008). "LTα and TNFR2 deficient mice resisted to ECM development, with no neurological signs up to day 22–25, at which time they succumbed of high parasitaemia and anemia (E and data not shown), consistent with published data." (PMID 18612394, 2008).
cerebral malaria (2 papers, 2008 to 2010). A sequestration of Plasmodium falciparum in the brain, which can cause coma and/or seizures. "LTα and TNFR2 signaling have been shown to be critical for Plasmodium berghei ANKA (PbA) induced ECM, as mice deficient for either LTα or TNFR2 are resistant to cerebral malaria, while TNFR1 is dispensable." (PMID 18612394, 2008). "TNF-related lymphotoxin α (LTα) is essential for the development of Plasmodium berghei ANKA (PbA)-induced experimental cerebral malaria (ECM)." (PMID 18612394, 2008). "Previous studies indicate that tumour necrosis factor (TNF) and lymphotoxin alpha (LTα) may be important for the development of cerebral malaria (CM) and other SM syndromes." (PMID 21029472, 2010). "Association between TNF/LTα polymorphism and increased risk of cerebral malaria has been reported, however more investigations are necessary to fully decipher the molecular bases of the link between disease manifestation and TNF/LTα polymorphism." (PMID 18612394, 2008). "Importantly, LTα, not TNF, has been shown to be a critical factor in the development of experimental cerebral malaria in C57BL/6 mice, identifying LTA along with TNF as a candidate susceptibility gene." (PMID 21029472, 2010).
degenerative disc disease (2 papers, 2014 to 2021). "These cases not only indicated the value of anti-LTα therapy in immunoinflammatory diseases but also provided new insights and inspiration for a combined anti-TNFα and anti-LTα treatment for degenerative disc diseases." (PMID 33441130, 2021). "The toxicity of LTα is much lower than that of TNFα, indicating that LTα may have a potential value in the development of disc degeneration models." (PMID 33441130, 2021).
dengue (2 papers, 2025). "Multiple HLA alleles have been identified as factors of susceptibility or protection against dengue across diverse populations, including HLA class I and II alleles and proteins like MICA, MICB, and LTA." (PMID 40006967, 2025).
autoimmune pancreatitis (1 paper, 2024). "Meanwhile, according to a study conducted on autoimmune pancreatitis (AIP), a common feature in IgG4-RD, it is observed that LTα and LTβ are overexpressed and positively correlate with CXCL13 expression." (PMID 38911857, 2024).
babesiosis (1 paper, 2024). Babesiosis refers to a condition caused by microscopic parasites that infect the red blood cells. "Our data suggest that an impaired cytokine response, including TNFα or LTα, may also contribute to parasite persistence, but more data in humans with babesiosis and polymorphisms that impact TNFα are needed." (PMID 39452729, 2024).
dyslipidemia (1 paper, 2013). "Recent clinical studies demonstrate LTα gene variability is also associated with metabolic syndrome features, including increased C-reactive protein, hyperinsulinemia, and dyslipidemia." (PMID 23704873, 2013).
experimental autoimmune encephalomyelitis (1 paper, 2013). An autoimmune demyelinating disease of the central nervous system that is produced experimentally in animals by the injection of homogenized brain or spinal cord in Freund's adjuvant. "Growing evidence supports a proinflammatory role of LTα, e.g. shown in studies of collagen-induced arthritis (CIA) and experimental autoimmune encephalomyelitis (EAE)." (PMID 23977237, 2013).
hair disorders (1 paper, 2022). "LTα may activate NF-kappaB-signaling pathway and implicate the control of normal hair follicle development and the pathophysiology of certain hair disorders." (PMID 35524260, 2022).
helminth infections (1 paper, 2023). "In the present study we found associations between SNPs in cytokines LTα and IFNβ1 and susceptibility to helminth infections but not to microparasites (bacteria and protists)." (PMID 36693052, 2023).
hypoadiponectinemia (1 paper, 2020). "Therefore, a therapy combining anti-TNF-α and anti-lymphotoxin alpha could restore APN serum levels in patients with hypoadiponectinemia verified in cases of IRS." (PMID 32876087, 2020).
ileitis (1 paper, 2024). "Recipients of 10%/90% mixtures of LTα−/−/μMT-TNFΔARE/+ and LTβ−/−/μMT-TNFΔARE/+ BM should also be impacted by TNFΔARE/+ induced ileitis, but for these mixtures, all B cells would lack either LTa or LTb." (PMID 38464070, 2024).
Immunodeficiency (1 paper, 2008). Failure of the immune system to protect the body adequately from infection, due to the absence or insufficiency of some component process or substance. "Wild-type bone marrow reconstitution in TNF/LTα deficient mice, that corrects immunodeficiency but not LN formation, could not restore their sensitivity to ECM." (PMID 18612394, 2008).
Kawasaki disease (1 paper, 2022). A rare inflammatory disease characterized by an acute febrile, systemic, self-limiting, medium-vessel vasculitis primarily affecting children. "MPO showed association with the products of three Kawasaki disease genes (FCGR2A, CASP3, and LTA) and one related to MIS-C (CYBB)." (PMID 36510129, 2022).
leishmaniasis (1 paper, 2020). Infectious disease that is transmitted through the bite of hematophagous female phlebotomine sand flies. "While the role of other family members has not been explored in leishmaniasis, LTα/LTβ (TNF-β and TNF-γ, respectively) has been explored by its interaction to form membrane-bound LTα1β2." (PMID 33415318, 2020).
lung disease (1 paper, 2013). "At the same time, highly conserved ancestral haplotype (AH) 8.1 including among others TNFα308A and LTα + 252 G alleles, is an important genetic modifier of lung disease in CF." (PMID 23343370, 2013).
marginal zone lymphoma (1 paper, 2009). A usually indolent mature B-cell lymphoma, arising from the marginal zone of lymphoid tissues. "Specifically, we confirm that genetic variants in TNF/LTA (encoding for the proinflammatory cytokines TNF-α and LT-α) were most pronounced for DLBCL and marginal zone lymphoma." (PMID 19390683, 2009).
papilloma (1 paper, 2021). A benign epithelial neoplasm that projects above the surrounding epithelial surface and consists of villous or arborescent outgrowths of fibrovascular stroma. "Strikingly, in a DMBA/TPA-induced skin carcinogenesis mouse model LTα deficiency led to a dramatic increase in papilloma formation, suggesting that LTα can actually protect mice from chemically induced skin cancer." (PMID 33917839, 2021).
skin cancer (1 paper, 2021). "Finally, expression of IL-13, which has strong antitumor properties in the context of chemically induced skin cancer, was significantly decreased in the skin of LTα-deficient mice." (PMID 33917839, 2021).
skin infection (1 paper, 2023). An inflammatory process affecting the skin, caused by bacteria, viruses, parasites, or fungi. "Therefore, we cannot rule out a contribution of LTα to host defense against S. aureus skin infections." (PMID 37327341, 2023).
tongue-tumour (1 paper, 2023). "Since lymphotoxin α (LTα) was significantly increased in tissues with TLSs, we overexpressed LTα in SCC7 cells (a mouse-derived HNSCC cell line) and established tongue-tumour-bearing models." (PMID 36825382, 2023).
vulvar cancers (1 paper, 2015). "Of the thirty-two candidate genes involved in these pathways, including TLR3, NFκB1, NFκB2, RelA, RelB, TRAF3 and TRAF6, only a SNP in the 5' UTR of the lymphotoxin alpha (LTA; TNF superfamily member 1) was significantly associated with increased risks of cervical and vulvar cancers." (PMID 26008697, 2015).
tumor (140 papers, 1996 to 2026). "Animal models of secondary lymphoid organs deficiency, such as the splenectomized LTα −/− mice, have shown that the presence of tumor associated TLS is sufficient to induce effective antitumor immune responses." (PMID 35874810, 2022). "On the other hand, in a transgenic adenocarcinoma mouse model spontaneously progressing to prostate cancer, LTα deficiency rescued tumor-reactive T cells and effectively reduced cancer incidence." (PMID 33917839, 2021). "Growth factor-related genes are also associated with tumor metastasis, among which LTα, TNFRSF12α, TNFRSF25, TNFRSF4, and IRF9 can mediate HNSCC tumorigenesis and metastasis through the NF-κB signaling pathway." (PMID 33330624, 2020). "The LTα gene, associated with tumor progression and angiogenesis in cutaneous lymphomas, shows a significantly reduction in its expression in MDAKDTRAF3IP258." (PMID 32483202, 2020). "The LTA gene encodes a signaling protein nominated lymphotoxin alpha (LTA) that has a major function in preventing tumor growth, and destroying cancerous cells, and comprises 205 amino acids with a molecular mass of 22,297 Daltons [Data source: Uniprot database (P01374)]." (PMID 36929286, 2023). "Both LTβR- and RORγt+ LTα-deficient mice developed more tumors as compared with co-housed littermate control mice, clearly implicating the key role of LTαβ–LTβR signaling in tumor control." (PMID 33917839, 2021). "Previous studies using LTβR-/- and LTα-/- mice or WT mice treated with LTβR-Ig demonstrated loss of NK cell populations in the spleen, lung, blood and bone marrow as well as impairment of NK cell anti-tumor activities." (PMID 34335629, 2021). "The following combinations of main keywords were used: (LTA OR Lymphotoxin alpha OR TNF-β OR tumor necrosis factor-beta) AND (polymorphism OR mutation OR variation OR SNP OR genotype) AND (cancer OR tumor OR neoplasm OR malignancy OR carcinoma OR adenocarcinoma)." (PMID 32420584, 2020). "In this regard, in a murine model of metastatic melanoma, the use of a LTα fusion protein induces the formation of lymphoid structures in the tumor bed, where tumor antigen-specific lymphocytes are generated." (PMID 37622111, 2023). "A unique observation of our study is the substantial overlap of genes involved in tumor manifestation/association with the genes involved in cardiotoxicity and neurotoxicity such as ESR1, PTGS2, LTA and KDR." (PMID 37069190, 2023). "Tumour-targeted lymphotoxin-alpha induced the de novo formation of lymphoid tissue with high endothelial venules, improving the anti-tumour responses, even in lymphoid-organ-depleted animals." (PMID 35205725, 2022). "MECA-79+ TA-HEVs were first observed in mice following various treatments such as adoptive transfer of CD8+ T cells, administration of tumor-targeted LTα or genetic depletion of Foxp3+ regulatory T cells (Tregs)." (PMID 33956259, 2021). "Consistent with this, tumors of mice treated with tumor-targeted LTα or bearing cancer cells genetically engineered to secrete LTα develop MECA-79+ TA-HEVs whereas control tumors are devoid of such vessels." (PMID 33956259, 2021). "In the subsequent functional analyses with GRACE, we showed that both SLAMF7 and LTA were co-expressed in tumor samples consistent with the results by WGCNA." (PMID 33403041, 2021). "It was shown that tumor clearance through GVL is dependent on both LTα and TNF expressed by donor cells, which induce apoptosis of recipient leukemic cells via TNFR1." (PMID 33917839, 2021). "Targeting an LTα fusion protein to the tumor site has been shown to be another strategy to successfully induce MECA79+ HEVs and lymphoid aggregates in the tumor microenvironment." (PMID 34484246, 2021). "After an encounter with CCR9lo tumour cells, genes involved in the positive regulation of the immune response, such as lymphotoxin alpha (LTA) and integrin alpha-2 (ITGA2), were over-expressed in CTL." (PMID 26861383, 2016).